TBX21 (T-box transcription factor 21)
Diseases named in the same sentence as TBX21 in open-access papers (continued):
Sharing a sentence is not in itself a finding about the gene and the disease.
tumor (continued). "With increasing levels of tumor PD-L1, the expression of transcription factors for Th1, Th2, or M1 macrophages, including NFKB1, GATA3, HIF1A, STAT4, TBX21, IRF8, and STAT1, was downregulated." (PMID 33754038, 2021). "We found that numerous NK cell effector function-related genes, such as TBX21, FYN, NCR1, SH2D1A, SH2D1B, PTPN6, and IL18RAP, were downregulated in tumor-infiltrating NK cells." (PMID 34535671, 2021). "As a result, we discovered that both the mRNA and protein expression of TBX21, SOX2 and OCT4 in SP cells derived from A549-shTBX21 tumor were significantly declined compared with those from A549-sc tumor (P < 0.01)." (PMID 29615105, 2018). "The TBX21 transcript was significantly downregulated (3 fold) in SN CD8+ T cells compared to PBMC (p<0.01) and in the CD8+ T cells from the tumor (p<0.01)." (PMID 29966014, 2018). "The results indicated a negative correlation between high TNM stage in tumor samples and elevated TBX21 expression." (PMID 39744435, 2025). "To determine whether findings from tumor samples could be replicated in CRC cell lines, we used qPCR and western blotting to examine TBX21 expression levels in normal colon cells and CRC cell lines." (PMID 39744435, 2025). "Collectively, these findings suggest that TBX21 expression is downregulated in human CRC tissues and that TBX21 may act as a potential tumor suppressor in CRC metastasis." (PMID 39744435, 2025). "Furthermore, levels of apoptosis related proteins in tumor tissues, including Bim, BID, and BAD, were sharply boosted by sh-TBX21 injection." (PMID 41573646, 2025). "We further analyzed the relationship between TBX21 expression and TNM stage in tumor samples." (PMID 39744435, 2025). "To validate our hypothesis regarding the importance of TBX21 in TEX in CRC, we explored publicly available scRNAseq data from 23 CRC patients with 65,362 matched normal and tumor single cells." (PMID 36230517, 2022). "In line with expression of ABCG2 and OCT4, expression of TBX21 was significantly higher in SP cells (P < 0.0001) and tumor spheres (P < 0.0001) compared with non-SP cells or nonspheres." (PMID 29615105, 2018). "Additionally, western blot analysis was performed on 10 pairs of fresh CRC and adjacent non-tumor tissues to further validate these findings, revealing reduced TBX21 levels in CRC tissues and higher levels in adjacent non-tumor tissues." (PMID 39744435, 2025). "Using isolated tumor tissue, we analyzed gene expression related to cytotoxicity (Perforin, Granzyme B, Granulysin, and FasL), inflammatory or chemotactic cytokines (IFN-γ, CXCL9, CXCL10, and CXCL11), and CD8+ T cell activation and proliferation (CD69, Tbx21, IL-2, and IL-12b)." (PMID 39066478, 2024). "Moreover, TBX21, known as a transcription factor of IFN-Ɣ, already showed a negative association with NSCLC prognosis by mediating tumor growth." (PMID 37726776, 2023). "The expression of T cell cytotoxicity (CD3G, CD3E, CD4, GZMA, PRF1 and TBX21), B cell MHC II and immune exhausted-related genes were abundant in metastatic sites; while MHC I inflammation related genes (HLA-B, HLA-C and IL-1A) were mostly higher in primary than recurrent tumor sites." (PMID 33476333, 2021). "Moreover, activated NK cells could mediate apoptosis of tumor cells through the expression of transcription factors TBX21 and EOMES, factors that can regulate the high expression of cytokines (e.g., IFN-γ and TNF-α) and exert anti-tumor effects through immunomodulatory effects." (PMID 39076970, 2024). "Then, we compared the expression of TBX21, EOMES, IFN-γ, and GZMM in the ESCA tumor tissue among the NICT, NCT, and NONE groups by immunofluorescent staining and qRT-PCR." (PMID 39076970, 2024). "In tumor tissue, Methylibium demonstrated significant negative correlations with ICOS and TBX21 expression and with T-cell abundance." (PMID 33863341, 2021).
tumor (continued). "Following the injection of sh-TBX21, no significant changes were observed on the clusters of PD-1+CD4+ T cells, Tim-3+CD4+ T cells, Lag-3+CD4+ T cells, PD-1+CD8+ T cells, Tim-3+CD8+ T cells, and Lag-3+CD8+ T cells in tumor tissues." (PMID 41573646, 2025).
infection (59 papers, 2010 to 2025). The state of being infected such as from the introduction of a foreign agent such as serum, vaccine, antigenic substance or organism. "In summary, loss of a Tbx21 allele or timely induction of Eomes in activated CD4 T cells has no profound effect on the distribution during the early phase of an acute infection." (PMID 36756120, 2023). "The importance of each Th subset was validated in Tbx21–/– and Rorc–/– mice where bacterial abundance was significantly higher in both strains at day 14 after infection, although leukocyte recruitment was largely unaffected." (PMID 39989461, 2025). "The M2 infection module revealed Chil3, Il4, Cx3cr1, Emr1 and Ccl2 as hubs, while module M6, associated with vaccination, disclosed Prf1, Klrc1, IFN-γ, Ncr1 and Tbx21 as hub proteins." (PMID 39563428, 2024). "Analysis of mice that fate map T-bet expression confirmed that Klrg1+aaMAIT cells were Tbx21-reporter positive, and also expressed T-bet protein at 40 days post infection." (PMID 37231163, 2023). "Between month 6 and month 12 post-infection, persistent Bm cell clones upregulated genes associated with CD21–CD27–FcRL5+ Bm cells, including TBX21, ITGAX and FCRL5." (PMID 37106039, 2023). "In another murine infection model, others further demonstrated that TBX21 appeared to be a critical regulator of PD-1 expression and was susceptible to epigenetic disruption impacting CD8 T cell exhaustion." (PMID 36230517, 2022). "Further work has then developed the story into showing clearly important roles for TBX21 in the regulation of interferon-γ production by regulating the accessibility of the IFNG gene through chromatin remodeling in the context of infection." (PMID 36230517, 2022). "A detailed analysis of inflammatory DCs present at the site of infection revealed that as early as day 3 post-infection, there was a noticeable reduction in DCs analyzed in Tbx21-/- mice when compared to WT mice." (PMID 33465134, 2021). "We have reported previously that mice with a germline depletion of Tbx21 are more resistant to an infection with this parasite due to a promoted type 2 immune response." (PMID 34795671, 2021). "Together, these data suggest that this DMR plays a critical role for the epigenetic control of Tbx21 expression and that the Tbx21 locus is already epigenetically remodeled in T-bet+ subsets at early time points of the infection." (PMID 34299148, 2021). "This was evident from comparative analysis of IFN-γ production by NK cells in WT and Tbx21-/- mice on days 3 and 5 post-infection." (PMID 33465134, 2021). "We therefore investigated its redundancy in LCMV WE low dose infection, which is usually controlled within 8 days after infection in Tbx21+/+ wild type mice." (PMID 32991634, 2020). "On day 8 after infection less than 20% of the transferred CTLs from P14 Tbx21+/+ and Tbx21-/- expressed Eomes, whereas CTLs from P14 Tbx21E/E mice were uniformly Eomes+ and mCherry+." (PMID 32991634, 2020). "C5 was also increased in the infected samples, and these cells co-expressed Eomes and Itga1, and were especially prominent in the infected Tbx21-/- sample, suggesting that this cluster includes the Eomes+ CD49a+ cells that arose in the liver after infection." (PMID 31393266, 2019). "tbx21 expression was induced upon infection (P<0.0001), as was the expression of il10 (P=0.004), while the expression of the other Th2 markers tested remained relatively constant." (PMID 29590635, 2018). "Both, the mRNA for the transcription factor (Tbx21) and cytokine (ifng) which characterize Th1 cells appeared in increased levels at weeks 6 and 10 after infection." (PMID 30410119, 2018). "Tbx21 (T-bet) mRNA levels were assessed by qRT-PCR in total RNA from scrambled ctrl OT-I and miR-155-OE OT-I cells sorted from the lungs on day 9 post-infection." (PMID 29358931, 2017).
infection (continued). "Notably, Th1 and Th17 subsets remained stable after infection, supported by the unchanged expression of their signature transcriptional regulators (tbx21 and rorc) and effector cytokines (ifng and il17a/f1)." (PMID 40821846, 2025). "Finally, an adoptive transfer of ILC1 into Tbx21-/- mice restored inflammatory DCs at the site of infection." (PMID 33465134, 2021). "Herein we demonstrate that Tbx21-/- mice succumb to infection significantly quicker than mice lacking T cells, suggesting an innate T-bet-dependent mechanism of host immunity, critical for survival of the acute stage of infection." (PMID 33465134, 2021). "Further corroborating this notion, induced depletion of T-bet had no impact on a subsequent infection with T. spiralis, and this stands in contrast to previous work showing that germline depletion of Tbx21 resulted in a more effective type 2 immune response upon infection with this parasite." (PMID 34795671, 2021). "Costimulatory molecules (CD80, CD86, CD40, GITR, and ICOS), adhesion molecules (VCAM-1 and P-selectin), and signaling molecules involved in cytokine regulation (Tbx21 and Socs1) were also increased with Hb infection and decreased with anti-IL-7Rα M595 treatment in a dose-dependent manner." (PMID 23057802, 2012). "Increased relative expression of TBX21 in Cm-infected WT animals could be in response to observed increased levels of IFN-γ in a fetuin-A-dependent manner that also impacts cell-mediated adaptive immunity in response to Cm infection." (PMID 35498397, 2022). "To more carefully investigate the influence of T-bet on TFH cell maintenance at the late phase of infection, we generated ERT2cre-Tbx21fl/fl mice (iTbx21−/−) by crossing Tbx21fl/fl mice with ERT2cre transgenic mice, in which Tbx21 gene knockout could be induced by tamoxifen treatment." (PMID 30984183, 2019). "We then went on to stringently test the functional redundancy of T-bet during acute infection with LCMV WE, by comparing Tbx21+/+ wild type with Tbx21-/- and Tbx21E/E mice." (PMID 32991634, 2020). "Also, clusters rich in Cd44, indicative of T cell activation, Tbx21, highlighting the TH1-dominated immune response after LCMV infection, and Lag3, an early exhaustion marker, were only present after infection." (PMID 41094201, 2025). "While most genes showed no significant change in expression upon infection, a few patterns emerged: TBX21 and IL-4 were slightly under-expressed in infected cells, while IL-33 was slightly over-expressed." (PMID 39273061, 2024). "Strikingly, T. gondii infection resulted in the rapid accumulation of inflammatory IRF8+ DCs in WT mice and this population was virtually absent in Tbx21-/- mice by day 8 post-infection." (PMID 33465134, 2021). "Consistent with flow cytometry analysis of T-bet/RORγt, the vast majority of MAIT cells detected during infection exhibited Tbx21 but not Rorc expression, consistent with a skewing towards a MAIT-1 response, and not MAIT-17." (PMID 34272362, 2021). "Besides, we also detected the expressions of T help cell differentiation-related transcription factors including TBX21 (T-bet), GATA3, and Foxp3 between CD4+CD8low+ double-positive T cells and CD8+ single-positive T cells after ALV-J infection." (PMID 34858872, 2021). "This was important, as neither Tbx21-/- nor Tbx21E/E mice were free of virus on day 8 after infection." (PMID 32991634, 2020). "Expression of Cd3d, Cd8a, Ifn, Ccl5 and Tbx21 remained highly upregulated 56 days post-infection whereas Ccr7 did not." (PMID 29040326, 2017). "The infection also activated the ZAP70/NF-κB pathway, essential for peripheral Th1 differentiation, as evidenced by p65 nuclear translocation and significant upregulation of Th1-related genes, including those of the transcription factor Tbx21 and interleukin-12 receptors." (PMID 40170858, 2025). "Next, using Tbx21-EYFP mice, we examined whether these cells upregulated T-bet during infection." (PMID 38687282, 2024).
cancer (28 papers, 2011 to 2025). A tumor composed of atypical neoplastic, often pleomorphic cells that invade other tissues. "The Th1 T cell differentiation phenotype, mediated by the expression of transcription factor T-bet (TBX21), is associated with favorable outcomes in patients with other cancers." (PMID 34943886, 2021). "Our results revealed that in malignant tumors compared to benign lesions or healthy tissue, there was a much higher expression of TBX21 encoding the Th1 cell-specific transcription factor T-bet." (PMID 32225066, 2020). "The correlation analysis indicated that the average expression of the five cancer stemness biomarkers was tightly associated with TBX21 in the integrated GEO dataset (r ≥ 0.850, P < 0.05)." (PMID 29615105, 2018). "Recently, an increased incidence of TBX21 has been linked to cancer development." (PMID 29615105, 2018). "However, the specific function of TBX21 associated with cancer stemness or the details remains unclear." (PMID 29615105, 2018). "While the functions and mechanisms of GSK3β are well-documented, its specific role in TBX21-mediated cancer metastasis remains unexamined." (PMID 39744435, 2025). "Many genes identified as TBX21 target genes using different cancer cohorts have been annotated as cancer related or immune related in the literature." (PMID 31227749, 2019). "Taken together, these data indicated that TBX21 promoted the cancer stemness of LUAD cells and played a positive role in maintaining LUAD cell development." (PMID 29615105, 2018). "All of the presented results prove that cancer stemness maintenance was governed by the TBX21–IL-4 pathway in LUAD cells." (PMID 29615105, 2018). "Taken together, a schematic model correlated with survival of LUAD patients was displayed focusing on the relationship between the TBX21–IL-4 signaling pathway and cancer stemness." (PMID 29615105, 2018). "Statistically significant associations, corrected for multiple testing, were observed for the transcripts TBX21 and TGFBR3, which are mediators of the immune system, and LGR6 and STX16 that have been repeatedly associated with cancer progression." (PMID 24194869, 2013). "Additionally, IL2RB, CD3E, and TBX21 showed significant enrichment in transcriptional misregulation in cancers and Th1 and Th2 cell differentiation pathways." (PMID 39974584, 2025). "In malignant tumors, the function of TBX21 is complex and variable, and its expression levels and activity may vary depending on the type and stage of cancer." (PMID 41573646, 2025). "The function of TBX21 is not limited to immune regulation but also involves the development of tissues such as the heart and skeletal muscle, and its abnormal expression is related to various diseases, such as autoimmune diseases and certain cancers." (PMID 41573646, 2025). "TBX21 was correlated with cancer stemness mediated by the TBX21-IL-4 pathway in LUAD patients." (PMID 37770496, 2023). "Lastly, we note that even if a citation is associated with many listed genes, the citations may not necessarily discuss the relationship between the cited gene and TBX21 in the context of the specific cancer type that the analysis was performed." (PMID 31227749, 2019). "Overall, our studies provide the first evidence that TBX21 promotes cancer stemness which may contribute to LUAD growth, metastasis and recurrence." (PMID 29615105, 2018). "Importantly, TBX21 induces cancer stemness biomarker (SOX2 and OCT4) alteration in LUAD cells and the mice model which is consistent with the acquisition of CSC maintenance." (PMID 29615105, 2018). "As previous studies proved that IL-4 with high expression value promoted cancer stemness and predicted the poor prognosis in cancers, the results indicated that cancer stemness might depend on the interaction between TBX21 and IL-4 in LUAD cells." (PMID 29615105, 2018). "Moreover, our functional data underscore that TBX21 promoted IL-4 expression and IL-4 signaling is indispensable for TBX21-mediated cancer cell stemness." (PMID 29615105, 2018).
cancer (continued). "In line with the result in vitro, these data indicated once again that TBX21 could improve the cancer stemness of LUAD cells and positively maintain LUAD development." (PMID 29615105, 2018). "In the process of module analysis and characteristic molecular screening, we selected two characteristic modules and 10 characteristic molecules (PTPRC, CD2, CD69, IRF8, CCR7, CCL5, il2rb, CXCL10, CCR5, TBX21), which could be used as biomarkers of cancer stem-like cells for GIST patients." (PMID 34925310, 2021). "So, we could infer that TBX21 might play a positive role in LUAD maintenance of cancer stemness." (PMID 29615105, 2018). "Based on previous studies, TBX21 (T-bet), PRDM1, and TOX have been reported to be transcriptionally regulated in neoantigen-specific TILs in cancer." (PMID 39870490, 2025). "The majority of the DEGs, e.g., SOX11, TBX21, FAM3B, FGF5, HNF1A, MYB, and PLAC8 have been reported to function as promoters or biomarkers in various cancer types." (PMID 34440579, 2021). "Based on regulon-level analysis of single-cell RNA-sequencing data, we found significantly lowered activity of the T-box TFs T-box 21 (TBX21) and eomesodermin (EOMES) in circulating CD8+ T cells and NK cells of the cancer-free TET2delA carriers." (PMID 30890702, 2019). "As an important feature of cancer stemness, self-renewal of LUAD cells was measured in the sphere formation experiment of A549 cells with sc or shRNAs for TBX21." (PMID 29615105, 2018). "However, the specific function of TBX21 correlated with cancer stemness remains unclear." (PMID 29615105, 2018). "Consistently, the expression of cancer stemness biomarkers, including SOX2 and OCT4, was decreased following the downregulation of TBX21 expression in western blot analyses." (PMID 29615105, 2018). "Collectively, our method reports a total of 17 genes as Down targets of TBX21 for STAD, which are unknown in immunology or cancer literature." (PMID 31227749, 2019). "We applied BioTarget to assess the activity of TBX21 and GATA3 pathways in cancers." (PMID 31227749, 2019). "Furthermore, TBX21 protein levels were evaluated in a panel of prostate cell lines, including normal prostate epithelial RWPE-1, AR-positive (LNCaP, 22RV1), and AR-negative (PC3, DU145) cancer cells." (PMID 41573646, 2025). "Akin to chronic viral infection and cancer systems, pop3 (KLRG1-CD62Lhi) exhibits the characteristics of stem-like progenitor CD8 T cells (high Tcf7, Slamf6, and Cxcr5 expression), whereas pop4 (KLRG1+CD62Lhi) closely resembles a transitory subset (elevated Tbx21, low Tcf1, and Tox expression)." (PMID 39975082, 2025). "TBX21 has been reported to be upregulated by stimuli such as TCR signalling and IFN-γ signalling, thereby supporting the hypothesis that ZNF683+ Trm cells are cancer-specific Trm cells." (PMID 36869093, 2023). "Interestingly, TBX21 expression was also higher in non-metastatic malignant tumors than those that are metastatic." (PMID 32225066, 2020). "Importantly, the prognostic power of this new model was derived from cancer stemness governed by the TBX21–IL-4 signaling pathway and was independent of the other clinical factors." (PMID 29615105, 2018).
bacterial infection (4 papers, 2018 to 2025). "TBX21 is an important transcription factor of adaptive immunity that regulates the Th1/Th2 balance and increasing evidence has pointed to the critical roles in regulating innate immunity, cytokine balance, immune dysregulation, and bacterial infection." (PMID 35401691, 2022).